TRMU (tRNA mitochondrial 2-thiouridylase)
Description:
Catalyzes the 2-thiolation of uridine at the wobble position (U34) of mitochondrial tRNA(Lys), tRNA(Glu) and tRNA(Gln). Required for the formation of 5-taurinomethyl-2-thiouridine (tm5s2U) of mitochondrial tRNA(Lys), tRNA(Glu), and tRNA(Gln) at the wobble position. ATP is required to activate the C2 atom of the wobble base.
Synonyms: MTU1; FLJ10140; MTO2; LCAL3; TRMT
Tractability: PROTAC: ubiquitination databases record sites on it; its protein half-life has been measured.
Gene: Protein-coding gene on chromosome 22 (46,330,875 to 46,357,344, forward strand). Ensembl gene ENSG00000100416.
Subcellular location: Mitochondrion
Subcellular location (Human Protein Atlas): Mitochondria
Pathways (Reactome):
Metabolism of RNA: tRNA modification in the mitochondrion
Gene Ontology:
Molecular function: protein binding; tRNA-5-taurinomethyluridine 2-sulfurtransferase; sulfurtransferase activity; transferase activity
Biological process: mitochondrial tRNA wobble position uridine thiolation; tRNA processing
Cellular component: mitochondrion
Genetic constraint (gnomAD): Loss-of-function variants: 49 observed, 48.73 expected, observed/expected ratio (o/e) 1.01, 90% interval 0.8 to 1.28. The upper end of that interval is the gene's LOEUF score, 1.28, which puts it in group 5 of 6, group 1 being the genes least tolerant of losing a copy. Missense variants: 572 observed, 548.38 expected, observed/expected ratio (o/e) 1.04, 90% interval 0.97 to 1.12. Synonymous variants: 241 observed, 205.97 expected, observed/expected ratio (o/e) 1.17, 90% interval 1.05 to 1.3.
Gene-disease validity (ClinGen):
ClinGen rates the evidence that TRMU causes each of these diseases.
mitochondrial disease (autosomal recessive): Definitive.
Leigh syndrome (autosomal recessive): Moderate. A progressive neurological disease defined by specific neuropathological features associating brainstem and basal ganglia lesions.
Homologues: Orthologues: chimpanzee TRMU (99% identical), macaque TRMU (95% identical), mouse Trmu (89% identical), rat Trmu (89% identical), pig TRMU (89% identical), guinea pig TRMU (87% identical), dog TRMU (87% identical), rabbit TRMU (83% identical), tropical clawed frog trmu (72% identical), zebrafish trmu (65% identical), Drosophila melanogaster CG3021 (40% identical), Caenorhabditis elegans mttu-1 (38% identical).
Diseases named in the same sentence as TRMU in open-access papers:
TRMU is named in the same sentence as 18 diseases in open-access papers, as found by Europe PMC text mining. Sharing a sentence is not in itself a finding about the gene and the disease. The quoted sentences say what the papers report.
deafness (3 papers, 2020 to 2023). An inherited or acquired condition characterized by the complete loss of the ability to hear from one or both ears. "To examine the roles of nuclear genes (GJB2, GJB3, GJB6 and TRMU) in the phenotypic manifestation of deafness-associated 12S rRNA mutations, we carried out a mutational screening of these genes in affected matrilineal relatives of three pedigrees." (PMID 32400865, 2020). "TRMU was identified as a nuclear modifier gene for the phenotypic expression of 12S mt-rRNA-related deafness; in particular, TRMU carrying the mutation p.Ala10Ser, leading to a mitochondrial translation impairment, and the A1555G mutation in 12S mt-rRNA modulates the manifestation of the pathology." (PMID 36768505, 2023). "To uncover the roles of nuclear gene mutations in deafness, we screened for the mutations in common deafness-associated genes (GJB2, GJB3, GJB6 SLC26A4 and TRMU) in the matrilineal relatives of the HZD055 and HZD510 pedigrees." (PMID 36292680, 2022). "To date, no mutations in MSS1 and TRMU allegedly associated with primary mitochondrial diseases have been modeled in yeast, although yeast has been used for studying a possible effect of mutations in the genes reported in this section with aminoglycoside-induced ototoxicity and deafness." (PMID 36768505, 2023).
Hearing impairment (3 papers, 2012 to 2022). A decreased magnitude of the sensory perception of sound. "To see whether nuclear genes (GJB2, GJB3, GJB6, and TRMU) mutations played active roles in clinical expression of hearing impairment, we initiated a mutational analysis of the exons of GJB2, GJB3, GJB6, and TRMU in matrilineal relatives of this pedigree." (PMID 34811812, 2022). "Furthermore, mutations in GJB2, GJB3, GJB6 and TRMU were implicated to be associated with hearing impairment." (PMID 32400865, 2020). "Indeed, the missense mutation c.G28T (p.A10S) of the TRMU gene has been reported in hearing loss patients with the A1555G mutation in some ethnic populations." (PMID 22879993, 2012). "Additionally, the A10S mutation of the TRMU gene has been reported to be a modifier gene in hearing loss with the A1555G mutation." (PMID 22879993, 2012).
liver failure (3 papers, 2016 to 2024). A liver disease characterized by the liver losing or has lost all of its function. "Differential diagnosis should also be considered with other mitochondrial disorders causing liver failure (MPV17, POLG1, POLG2, TFAM, TWNK, TRMU)." (PMID 38756539, 2024).
acute infantile liver failure (1 paper, 2022). "Studies have reported that mutations in TRMU cause acute infantile liver failure." (PMID 36686818, 2022).
acute liver failure (1 paper, 2023). Rapid deterioration of liver function causing encephalopathy and coagulopathy. "The combination of protein domain and variant distribution data as well as pathogenicity score modeling was applied in two different subtypes of acute liver failure in infancy caused by variants in the genes TRMU and LARS1 encoding for tRNA processing enzymes." (PMID 36789265, 2023).
liver disease (1 paper, 2011). "Genomic sequencing revealed compound heterozygous mutations in the mitochondrial transfer ribonucleic acid modifying factor (TRMU) in a single patient only, presenting with early onset, reversible liver disease." (PMID 21169334, 2011).
prostatitis (1 paper, 2025). An infectious or non-infectious inflammatory process affecting the prostate gland. "Our analysis revealed two Tier 2 genes (NOA1 and ELAC2) for BPH, two Tier 3 genes (TRMU and SFXN5) for prostatitis, and six Tier 3 genes (MRPL24, NDUFS6, PUS1, NBR1, GLOD4, and PCBD2) for PCa." (PMID 40919435, 2025). "We revealed two Tier 2 genes (NOA1 and ELAC2) and one Tier 3 gene (ACAT1) for BPH, two Tier 3 genes (TRMU and SFXN5) for prostatitis, and six Tier 3 genes (MRPL24, NDUFS6, PUS1, NBR1, GLOD4, and PCBD2) for PCa." (PMID 40919435, 2025).
cancer (3 papers, 2016 to 2024). A tumor composed of atypical neoplastic, often pleomorphic cells that invade other tissues. "Moreover, some other non-structural nuclear MTRGs, such as SUCLA2, DARS2, and TRMU, can regulate tumor cells and influence the prognosis of cancer patients." (PMID 34692528, 2021).
TRMU also shares sentences with these, for which no sentence is quoted: mitochondrial disease (3 papers); infantile liver failure (2); tumor (2); Encephalopathy (1); glycogen storage diseases (1); hepatocellular carcinoma (1); hydrops fetalis (1); hypertrophic cardiomyopathy (1); meningioma (1); Osteopenia (1).